CFTR (CF transmembrane conductance regulator)
Diseases named in the same sentence as CFTR in open-access papers (continued):
Sharing a sentence is not in itself a finding about the gene and the disease.
glioma (continued). "We have found in this study that CFTR protein expression is significantly higher in glioblastoma patients compared to low‐grade astrocytoma patients, supporting the promoting role of CFTR in glioma development." (PMID 32463592, 2020). "Our Western blot result showed that both band B and band C, which indicate the immature and mature isoforms of CFTR, respectively, could be detected by CFTR‐C in glioma cell lines." (PMID 32463592, 2020). "To test whether CFTR has similar function in vivo, we established both subcutaneous and orthotopic xenograft models using control or CFTR‐overexpressing U87 cells to evaluate the role of CFTR in glioma progression." (PMID 32463592, 2020). "We went further to examine whether dysfunction of CFTR affects glioma cell viability." (PMID 32463592, 2020). "Having established that CFTR regulates apoptotic response and promotes glioma progression, we asked whether the expression level of CFTR is significantly increased in malignant glioma patients and correlates with glioma grades." (PMID 32463592, 2020). "We first examined the expression levels of CFTR in different glioma cell lines (GBM cell lines U138 and U87, and grade III glioma cell lines SW1088 and SW1783) by real‐time PCR." (PMID 32463592, 2020). "Studies by Maertens and co-workers indicate that the chlorotoxin does not affect the current induced by the volume-regulated (VRCC), calcium-activated (CaCC), glioma-specific chloride channel (GCC) and the CFTR channel." (PMID 26848686, 2016). "ClTx itself is not a general Cl− channel blocker as native toxin applied extracellularly does not block volume-regulated, Ca2+-regulated, CFTR (cAMP-regulated) Cl− channels, and glioma-specific Cl− channels." (PMID 41150198, 2025). "Thus, it is plausible that CFTR and PI3K/Akt pathway constructs a positive feedback loop to promote glioma development." (PMID 32463592, 2020).
hepatocellular carcinoma (9 papers, 2018 to 2025). A malignant tumor that arises from hepatocytes. "Caco-2 cells are derived from a colorectal adenocarcinoma and express the CFTR gene, whereas HepG2 cells are derived from hepatocellular carcinoma and do not express the CFTR gene." (PMID 40332394, 2025). "Consistently, one study reported that CFTR was found to be aberrantly methylated in 100% of the cases studied (25 out of 25) of early stage hepatocellular carcinomas (HCCs) but not in healthy liver tissue, suggesting cancer-specific hypermethylation of CFTR." (PMID 32365523, 2020).
influenza (9 papers, 2015 to 2025). An acute viral infection of the respiratory tract, occurring in isolated cases, in epidemics, or in pandemics; it is caused by serologically different strains of viruses (influenzaviruses) designated A, B, and C, has a 3-day incubation period, and usually lasts for 3 to 10 days. "For example, the M2 protein of influenza A, the most common cause of influenza, both decreases CFTR activity and its expression." (PMID 41180002, 2025). "Reducing CFTR function in CF carriers who have only a 50% baseline level of CFTR function before an influenza infection could help explain why CF carriers are at increased risk for bacterial pneumonia." (PMID 41180002, 2025). "If people with CF are at increased risk for pulmonary exacerbations following an influenza infection, CF carriers, with just 1 CFTR gene mutation, may also be at increased risk for subsequent pulmonary infections following an influenza infection." (PMID 41180002, 2025). "Relevant to our findings for CF carriers, influenza infections particularly appear to inhibit CFTR activity." (PMID 41180002, 2025). "Influenza infection leads to reduced activity of airway CFTR by slowing its maturation, leading to a decrease in its function." (PMID 41011750, 2025). "The membrane protein (M2) of influenza A has intrinsic ion channel activity and also inhibits CFTR during infection." (PMID 36625656, 2023). "IAV M2 also downregulates the expression and function of two host ion channels, the amiloride-sensitive epithelial sodium channel (ENaC) and the cystic fibrosis transmembrane conductance regulator (CFTR) chloride channel, which promotes influenza pathogenesis." (PMID 35720341, 2022). "We have previously shown that influenza infection results in activation of A1-subtype adenosine receptors, which induces increased CFTR-mediated Cl− secretion." (PMID 25840995, 2015). "Multiple investigations indicate that influenza infections can adversely affect CFTR activity." (PMID 41180002, 2025). "The CFTR therapeutic lumacaftor can stabilize CFTR against degradation: its use in experimental settings restores airway cell function following in vitro influenza infection." (PMID 33250777, 2020). "AM2 also contributes to influenza pathogenesis by downregulating the expression and function of two host ion channels, the amiloride-sensitive epithelial sodium channels (ENaC) and the cystic fibrosis transmembrane conductance regulator (CFTR) chloride channels." (PMID 31261944, 2019). "We find that IAV infection consistently increases the bacterial burden of the human airway epithelium, that this increase is conveyed by various influenza strains, and that this increase is dependent on IAV-induced CFTR dysfunction and subsequent ASL acidification." (PMID 37318849, 2023).
ovarian carcinoma (9 papers, 2015 to 2024). A malignant neoplasm originating from the surface ovarian epithelium. "The top 10 genes with most deleterious mutations in the Chinese ovarian cancer population were MC1R (12%), MLH1 (9%), PRKDC (8%), KIF1B (8%), FANCM (7%), FANCI (6%), PRSS1 (6%), SDHA (6%), BRCA2 (6%), and CFTR (5%)." (PMID 38817903, 2024). "Considerably higher expression of CFTR in ovarian cancer was seen in vitro and in vivo, so downregulation of CFTR or dysfunctional CFTR should suppress aggressive malignant biological behaviors of ovarian cancer cells." (PMID 35042562, 2022).
primary ciliary dyskinesia (9 papers, 2014 to 2025). A rare, genetically heterogeneous, primarily respiratory disorder characterized by chronic upper and lower respiratory tract disease. "Differential diagnosis with ciliary dyskinesia was excluded, as was exon 2 skipping of CFTR gene that might have caused a CFTR functional defect." (PMID 24621136, 2014). "CFTR sequencing plus a ciliary dyskinesia gene panel were both negative, and nasal brushing electron microscopy did not support ciliary dyskinesia diagnosis either." (PMID 41229418, 2025). "This severe CRS led us to perform extensive CFTR genotyping as primary ciliary dyskinesia (PCD) diagnosis was unlikely due to lack of respiratory distress at birth, absence of middle ear involvement and inferior airway infections." (PMID 31788264, 2019).
cervical carcinoma (8 papers, 2014 to 2022). A carcinoma arising from either the exocervical squamous epithelium or the endocervical glandular epithelium. "Overexpression of CFTR was closely associated with cancer progression, aggressive behaviour and poor prognosis of cervical cancer, later associated with constitutive activation of NF-κB." (PMID 32365523, 2020). "It has also been demonstrated that the expression of CFTR is significantly increased and highly associated with cervical cancer progression, aggressive behaviors and poorer prognosis, accompanied by elevated expression of NFκB p65." (PMID 28978008, 2017). "In contrast, CFTR was found to be highly expressed in cervical cancer and associated with poor prognosis." (PMID 27769067, 2016). "In addition, CFTR expression was also reported to be associated with HPV infection in cervical carcinoma." (PMID 27769067, 2016). "Although further studies are needed to better understand this phenomenon, a possible explanation is that oestrogen, frequently abnormally increased in ovarian and cervical cancers, is known to stimulate CFTR expression, which could happen in this case." (PMID 32365523, 2020). "However, a positive link between CFTR and NFκB has been found in the embryo and cervical cancer." (PMID 28978008, 2017).
channelopathy (8 papers, 2013 to 2024). Channelopathies are a group of diseases caused by the dysfunction of ion channel subunits or their interacting proteins. "CF is a monogenic channelopathy caused by inactivating mutations in the CF transmembrane conductance regulator (CFTR) gene." (PMID 33135109, 2020). "Understanding the coordination of compartment-specific quality control systems along the secretory and endocytic pathways has the potential to contribute to improved therapeutic strategies for protein misfolding diseases like CFTR and other channelopathies." (PMID 23599894, 2013). "Considering CFTR as a pivotal determinant of bile secretion, CFLD is conceptualized as a “channelopathy”." (PMID 38473009, 2024).
congenital bilateral absence of vas deferens (8 papers, 2013 to 2025). Congenital bilateral absence of the vas deferens (CBAVD) is a condition leading to male infertility. "Such mutation was peculiar of a CFTR-RD patient that had Congenital Bilateral Absence of Vas Deferens (CBAVD), diffuse bronchiectasis, a borderline sweat chloride test and the heterozygous severe F508del mutation on the other allele." (PMID 23555973, 2013).
Constipation (8 papers, 2016 to 2025). Infrequent or difficult evacuation of feces. "Distal intestinal obstruction syndrome (DIOS)/constipation was reportedly treated prophylactically in CF transmembrane conductance regulator-knockout ferrets, but the medical intervention was used to manage the occasional DIOS/constipation episodes." (PMID 38532510, 2024). "Our patient presented with severe chronic constipation resistant to treatment, likely due to the concomitant CFTR-RD, which occasionally has been reported." (PMID 35627274, 2022). "Recognization of the role of CFTR and CaCC chloride channels in intestinal fluid secretion and motility modulation makes them promising molecular targets for constipation therapy." (PMID 28713271, 2017). "CFTR and CaCCs chloride ion channels have become important targets for the treatment of constipation in recent years." (PMID 27932986, 2016). "The better functioning of CFTR could have other various beneficial effects: by augmenting the fluid flow in the GI tract, it can lead to diminished constipation and SIBBO, thus leading to a better sense of appetite and less intestinal inflammation." (PMID 36771186, 2023). "In this study, we also found that Maren pills can upregulate the expression of PKA and CFTR proteins, which is consistent with the upregulated trend of AQP3, and jointly plays a regulatory role in constipation." (PMID 32774435, 2020). "The effectiveness of Urd and AELP on the cystic fibrosis transmembrane conductance regulator (CFTR) transcription for the Cl ion channel was detected in only the Lop-induced constipation model and not in the C3 KO model." (PMID 41011160, 2025).
gallstones (8 papers, 2014 to 2025). Solid crystalline precipitates in the biliary tract, usually formed in the gallbladder, resulting in the condition of cholelithiasis. "Five children had pancreas divisum, three had other abnormal findings, two had associated gallstones, and one had compound heterozygous cystic fibrosis transmembrane conductance regulator (CFTR) mutation." (PMID 35844741, 2022). "These loci are located in seven different genes, including SLC4A5, MUC4, FTO, NPC1 and FXYD2 genes that may increase the risk of gallstone in the Tibetan population, while CFTR and ADCY2 genes that reduce the risk of gallstone in the Tibetan population." (PMID 35651949, 2022). "Multiple “other factors” were (e.g. alcohol, gallstones, genetics [PRSS1, CFTR variants], and HTG)." (PMID 36046477, 2022). "Thus, the incidence of AP in the patients using a CFTR-modulator may be artificially increased by gallstone AP, therefore decreasing the estimate of the true effect CFTR-modulators on decreasing AP events." (PMID 36046477, 2022). "Recent experimental studies on mice with defects in the cystic fibrosis transmembrane conductance regulator gene (CFTR) have shown that bile salt malabsorption also occurs in these animal models, which may be caused by the disorder of mucin, and leads to gallstone." (PMID 25107305, 2014).
heart failure (8 papers, 2015 to 2022). Inability of the heart to pump blood at an adequate rate to meet tissue metabolic requirements. "Additionally, CAD and Heart Failure PheRS are significantly associated with rare variants in CFTR (p = 1.27E−06, p = 1.19E−06)." (PMID 34302027, 2021). "In the case of CFTR, its downregulation and reversal of its endo-epicardial gradient, which may contribute to the increased risk of arrhythmia in patients with heart failure, were described." (PMID 34831426, 2021). "Changes in heart failure were described primarily in relation to CFTR, CIC-2, CIC-3 channels, and calcium-activated chloride current." (PMID 34831426, 2021). "However, we have previously shown that experimental heart failure down-regulates CFTR expression in mice: we therefore cannot exclude that the patient’s medical condition significantly contributed to the observed phenotype." (PMID 26367262, 2015).
hyperglycaemia (8 papers, 2016 to 2025). "These evidences revealed that CDX2 interfered with β-catenin activation by positively regulating CFTR, ultimately inhibiting hyperglycemia-associated renal tubular lesions." (PMID 33621200, 2021). "Clinical remission of CFRD could be explained by the introduction of CFTR modulators at our centre in 2021, which likely improved pulmonary exacerbations and the hyperglycaemia associated with acute disease." (PMID 40430241, 2025). "CDX2 inhibited the increase of activated β-catenin and Snail to suppress hyperglycemia-associated RTECs injury and renal tubular-interstitial fibrosis, and it’s effects may rely on CFTR upregulation." (PMID 33621200, 2021). "This phenomenon was thought to be secondary to the impact of hyperglycemia on the cystic fibrosis transmembrane conductance regulator (CFTR), which has an integral role in airway barrier function." (PMID 36559113, 2022). "After CDX2 overexpression and knockdown of CFTR under HG conditions, CDX2 cannot present the suppression of Wnt/β-catenin signaling to inhibit hyperglycemia-associated renal tubular lesions." (PMID 33621200, 2021). "Similarly, the effects of hyperglycemia have also been investigated in 16HBE14o- cells expressing a modified CFTR, F508del/V470." (PMID 40565059, 2025).
phenylketonuria (8 papers, 2016 to 2025). Phenylketonuria (PKU) is the most common inborn error of amino acid metabolism and is characterized by mild to severe mental disability in untreated patients. "However, we found a number of VUS in such known genes, including ACADM, ACADVL and CFTR, and this has also been shown previously for other disease genes included in NBS panels, including PAH gene for phenylketonuria and GALT for galactosemia." (PMID 34449524, 2021).
pulmonary edema (7 papers, 2006 to 2022). Accumulation of fluid in the lung tissues causing disturbance of the gas exchange that may lead to respiratory failure. "The results were compatible with an inhibition of epithelial chloride transport through the CFTR and a sodium potassium ATPase dysfunction in children with meningococcal septicemia induced pulmonary edema." (PMID 16571116, 2006). "CFTR is a miRNA-223-3p target involved in the resolution of pulmonary edema." (PMID 35229638, 2022). "The secretion of alveolar fluid, caused by inhibiting Na+ entry, is sensitive to inhibition of CFTR, NKCC, or Na+-K+-ATPase, suggesting that CFTR, NKCC or Na+-K+-ATPase inhibitors may have potential in treating pulmonary edema caused by low expression of ENaC." (PMID 34163357, 2021). "Expression and function of both NKCC1 and CFTR can be modulated by released cytokines; however, the relevance of this modulation in the context of ARDS and pulmonary edema is so far unclear." (PMID 28439270, 2017). "There is evidence that in alveolar epithelial cells as opposed to upper airways epithelia a reduction in CFTR function is linked to a reduction in sodium transport through ENaC, which may contribute to the reduced lung liquid clearance observed in pulmonary edema." (PMID 16571116, 2006). "TNF-α can also alter sodium uptake and chloride secretion by reducing the expression of the ENaC mRNA and the stability of the cystic fibrosis transmembrane conductance regulator (CFTR) as a chloride channel, which can result in higher airway liquid film depth and pulmonary edema." (PMID 35337387, 2022). "CFTR and NKCC inhibitors show promise in treating pulmonary edema." (PMID 34163357, 2021).
type 2 diabetes (7 papers, 2021 to 2026). "Metformin is a biguanide drug, which is used in type 2 diabetes, Metformin activates 5′AMP-activated protein kinase (AMPK) that inhibits CFTR by phosphorylation which leads to the suppression of epithelial fluid and electrolyte secretion." (PMID 35328738, 2022). "CY-09, an analog of cystic fibrosis transmembrane conductance regulator (CFTR) inhibitor-172 (C172), blocks ATP binding with NLRP3 by directly binding to the NLRP3 Walker A motif, showing protective effects in mice models of gout and Types 2 diabetes." (PMID 35741054, 2022). "Among contributors to the development of CFRD, in addition to CFTR genotype, there are other genetic factors related and not related to type 2 diabetes." (PMID 33810109, 2021).
alcohol abuse (6 papers, 2015 to 2025). The use of alcoholic beverages to excess, either on individual occasions ("binge drinking") or as a regular practice. "Furthermore, genetic testing for SPINK1 and CFTR variants—identified in 22% of idiopathic RAP cases—may help identify high-risk individuals even in the absence of alcohol abuse." (PMID 41227226, 2025). "The present findings demonstrated that chronic alcohol abuse modified the expression of genes ITLN1 and CFTR in WT mice intestines with minor changes in TLR4-KO compared to the untreated control mice." (PMID 34884634, 2021).
celiac disease (6 papers, 2019 to 2024). An autoimmune genetic disorder with an unknown pattern of inheritance that primarily affects the digestive tract. "Recently, we reported that mice bearing defective CFTR are abnormally susceptible to a celiac disease-like enteropathy, in thus far that oral challenge with the gluten derivative gliadin elicits an inflammatory response." (PMID 30874543, 2019). "Recent evidence indicates that CFTR is inhibited by a gluten/gliadin-derived peptide (P31-43), causing an acquired state of CFTR inhibition within the gut that contributes to the pathogenesis of celiac disease (CD)." (PMID 30737369, 2019). "A recent study indicates that the gluten/gliadin-derived peptide (P31-43) can cause CFTR inhibition in intestinal epithelial cells, thus causing a local stress response that contributes to the immunopathology of celiac disease (CD)." (PMID 30898172, 2019). "Several studies indicate that patients with CF have a higher incidence of celiac disease (CD) and that mice bearing genetically determined CFTR defects are particularly sensitive to the enteropathogenic effects of the orally supplied gliadin (a gluten-derived protein)." (PMID 31321000, 2019).